FOXQ1 (forkhead box Q1)
Diseases named in the same sentence as FOXQ1 in open-access papers (continued):
Sharing a sentence is not in itself a finding about the gene and the disease.
adenoma (4 papers, 2010 to 2024). A neoplasm arising from the epithelium. "Genes associated with the recurrent gained VELs shared between CRC and the adenomas included FOXQ1 and RASGRF1 (right)." (PMID 28169291, 2017). "Of these genes, our study found that KIAA1199, FOXQ1 and IL8 were differentially expressed in adenomas (and in cancers) relative to normal controls." (PMID 22276102, 2012).
esophageal cancer (4 papers, 2017 to 2025). A primary or metastatic malignant neoplasm involving the esophagus. "For instance, FOXQ1 expression was positively correlated with T regulatory cells (T regs) in esophageal carcinoma." (PMID 36118871, 2022). "FOXQ1 upregulated in esophageal cancer can facilitate cell proliferation, migration, and invasion in esophageal cancer by reducing the expression of CDH116." (PMID 33483471, 2021). "To this end, we first measured FOXQ1 protein level in 5 human esophageal cancer cell lines (EC1, EC109, EC9706, TE1 and TE13) and the normal human esophageal epithelial cell line HET-1A." (PMID 28726780, 2017). "In the present study, we also noticed that FOXQ1 highly expressed in all the 5 human esophageal cancer cell lines." (PMID 28726780, 2017). "In this study, we also identified that FOXQ1 highly expressed in human esophageal cancer cells and that FOXQ1 silence inhibited the tumor cell growth both in vitro and in vivo." (PMID 28726780, 2017). "Compared with the corresponding tumor cells transduced with empty control vector, the growth of human esophageal cancer cells was retarded in the FOXQ1 silencing vector-expressing EC109 and EC9706 cells both in vitro and in vivo." (PMID 28726780, 2017). "The relative level of FOXQ1 protein was higher in all the esophageal cancer cell lines than that of the HET-1A cells." (PMID 28726780, 2017). "Given that our in vitro studies suggested a functional role for FOXQ1 in the esophageal cancer cell proliferation, we next investigated the contribution of FOXQ1 to the esophageal cancer cell growth in vivo." (PMID 28726780, 2017). "Taken together, these results suggested that FOXQ1 might promote cell proliferation and tumourigenicity of the esophageal cancer cells in vivo." (PMID 28726780, 2017). "In addition, FOXQ1 overexpressed in human esophageal cancer cells and ablation of FOXQ1 restrained the tumourigenic ability of the esophageal cancer cells (EC109 and EC9706) in a mouse xenograft model in vivo." (PMID 28726780, 2017). "Moreover, we showed that FOXQ1 protein level was elevated in human esophageal cancer cells and the tumourigenic ability of FOXQ1 in the cancer cells was confirmed in a mouse xenograft model in vivo." (PMID 28726780, 2017).
glioblastoma (4 papers, 2013 to 2022). The most malignant astrocytic tumor (WHO grade IV). "FOXQ1 expression was related to a favorable PFS in glioblastoma multiforme and corpus endometrial carcinoma." (PMID 36118871, 2022). "Cox regression analysis demonstrated that FOXQ1 expression was associated with a benign PFS in uterine corpus endometrial carcinoma, kidney renal papillary cell carcinoma, and glioblastoma multiforme and a poor PFS in pancreatic adenocarcinoma." (PMID 36118871, 2022). "Our results indicate that inhibition of FoxQ1 expression significantly suppresses the tumorigenicity of human glioblastoma cells, whereas rescue the NRXN3 expression can recover the ability of tumorigenicity." (PMID 23383267, 2013). "Our results indicate that suppression of FoxQ1 expression increase NRXN3 expression in glioblastoma cells." (PMID 23383267, 2013). "Our RT-qPCR analyses showed a significant association between FoxQ1 overexpression and decreased NRXN3 expression in 30 matched primary glioblastoma tissues and the adjacent normal brain tissues and Western blot further confirmed the correlation in 6 matched specimens." (PMID 23383267, 2013). "We first determined the FoxQ1 and NRXN3 mRNA expression in 30 human glioblastoma and the paired adjacent normal brain specimens by RT-qPCR analyses." (PMID 23383267, 2013).
melanoma (4 papers, 2023 to 2025). A malignant, usually aggressive tumor composed of atypical, neoplastic melanocytes. "The transcription factor FOXQ1 suppresses the progression of the same process in melanoma cells that induce carcinogenesis, a process dependent on the balance between two types of proteins: β-catenin and members of the TLE family." (PMID 41347087, 2025). "Lower expression of FOXQ1 was also observed in remote metastases of cutaneous melanomas, and FOXQ1 over-expression reduced melanoma tumour growth in mouse xenograft models." (PMID 39777582, 2025). "An alternative strategy may be to “repurpose” FOXQ1 as a tumour suppressor, considering its tumour-inhibiting role in melanomas." (PMID 39777582, 2025). "Evidence from melanoma suggests that FOXQ1 can suppress the EMT of melanocytes." (PMID 39777582, 2025). "MITF itself acts as a tumour suppressor in melanomas by inhibiting EMT and cell invasion, suggesting that the effect of FOXQ1 on melanoma progression is controlled by multiple converging mechanism that may not occur in other cell types." (PMID 39777582, 2025). "Indeed, overexpression of β-catenin in melanoma cells displaced TLE from FOXQ1 at the N-cadherin promoter and thereby activated N-cadherin expression." (PMID 39777582, 2025). "This was largely sufficient to override the tumour suppressor function of FOXQ1 in melanoma cells, indicating that the differential regulation of just one gene may decide the context-dependent role of FOXQ1 in cancer." (PMID 39777582, 2025). "On the other hand, FOXQ1 may also act as a tumor suppressor in other types of cancer such as melanomas, which is thought to depend on the recruitment of different transcription cofactors." (PMID 38432629, 2024). "Similarly, FOXQ1 has opposing functions in carcinoma and melanoma cells, which may be mediated by the cell type–dependent recruitment of β-catenin." (PMID 37011861, 2023).
lung adenocarcinoma (3 papers, 2012 to 2022). A carcinoma that arises from the lung and is characterized by the presence of malignant glandular epithelial cells. "The results proved that FOXQ1 expression was positively correlated with the stromal and immune score in breast invasive carcinoma, prostate adenocarcinoma, thyroid carcinoma, lung adenocarcinoma, and ovarian serous cystadenocarcinoma." (PMID 36118871, 2022). "At the tissue level, TCGA and Oncomine databases showed that FOXQ1 was upregulated in colon adenocarcinoma, lung adenocarcinoma, lung squamous cell carcinoma, thyroid carcinoma, and liver hepatocellular carcinoma and downregulated in kidney cancer and prostate adenocarcinoma." (PMID 36118871, 2022). "Thus, our present results corroborate previous findings regarding FoxQ1 expression in NSCLC, especially in lung adenocarcinoma." (PMID 22761930, 2012).
lymph node metastasis (3 papers, 2017 to 2023). "High FOXQ1 expression was significantly associated with increased lymph node metastasis." (PMID 29050264, 2017). "The expression of FOXQ1 was demonstrated to be positively correlated with lymph node metastasis and TNM stage." (PMID 33330033, 2020). "Furthermore, the overexpression of FOXQ1 was significantly correlated with lymph node metastasis or higher TNM stage, which is consistent with our previous study." (PMID 33330033, 2020).
non-small cell lung carcinoma (3 papers, 2012 to 2013). A group of at least three distinct histological types of lung cancer, including non-small cell squamous cell carcinoma, adenocarcinoma, and large cell carcinoma. "Overexpression of FOXQ1 has been found in a variety of human cancers, and its upregulation has been associated with poor prognosis in colorectal, breast, and non-small cell lung carcinomas." (PMID 23203039, 2012).
squamous cell carcinoma (3 papers, 2012 to 2025). A carcinoma arising from squamous epithelial cells. "Expression of FoxQ1 in adenocarcinoma was higher than in squamous cell carcinoma (P = 0.005), and high expression of FoxQ1 correlated with loss of E-cad expression (P = 0.012), and anomalous positivity of VIM (P = 0.024) and S100A4 (P = 0.004)." (PMID 22761930, 2012). "HNRNPA2B1 was found to bind to FOXQ1 mRNA in squamous cell carcinoma cells, presumably via a methylated consensus RNA motif, and increased FOXQ1 transcript and protein levels." (PMID 39777582, 2025). "Higher expression of FoxQ1 in adenocarcinoma than squamous cell carcinoma was verified, and four adenocarcinoma cell lines were used to model the potential proliferative role of FoxQ1 silencing or overexpression in NSCLC." (PMID 25356753, 2014). "The expression of FoxQ1 in adenocarcinoma was higher than in squamous cell carcinoma, and FoxQ1 overexpression influenced poor prognosis in NSCLC and was associated with EMT." (PMID 25356753, 2014). "FoxQ1 protein expression in adenocarcinoma was higher than in squamous cell carcinoma with statistical significance (χ2 = 10.7089, P = 0.005) by χ2 test analysis." (PMID 22761930, 2012).
triple-negative breast carcinoma (3 papers, 2022 to 2025). An invasive breast carcinoma which is negative for expression of estrogen receptor (ER), progesterone receptor (PR), and human epidermal growth factor receptor 2 (HER2). "For instance, HuR stabilizes forkhead box Q1 (FOXQ1) mRNA in MDA-MB-231 triple-negative breast cancer cells, promoting tumorigenesis and metastases, and stabilizes TGFB mRNA in activated HSCs, contributing to fibrosis in chronic liver disease." (PMID 40809813, 2025). "Our study suggests that targeting the FOXQ1-MLL epigenetic axis could be a promising strategy to combat triple-negative breast cancer metastatic progression." (PMID 36319643, 2022). "Further analysis identified DDR2 as the most upregulated receptor tyrosine kinase and a shared downstream effector of FOXQ1 and SNAI1 in triple-negative breast cancer (TNBC) cell lines." (PMID 36713812, 2022).
acute kidney injury (2 papers, 2025). Sudden and sustained deterioration of the kidney function characterized by decreased glomerular filtration rate, increased serum creatinine or oliguria. "Recent research reports USP10 deubiquitinating regulates FOXQ1, which plays a protective role in sepsis-induced acute kidney injury (S-AKI) by inducing inflammation and apoptosis." (PMID 41347087, 2025).
Alzheimer disease (2 papers, 2019 to 2020). A progressive, neurodegenerative disease characterized by loss of function and death of nerve cells in several areas of the brain leading to loss of cognitive function such as memory and language. "Overexpression of FOXQ1 inhibited the senescence and improved the migration of human umbilical cord MSCs in vitro and in vivo, thus promoting their therapeutic efficacy in an animal model of Alzheimer's disease." (PMID 31881006, 2019).
atopic dermatitis (2 papers, 2017 to 2021). "Here, we show that cytokine IL-4 which is implicated in the development of chronic inflammatory disease atopic dermatitis (AD) induces expression of transcription factor FoxQ1 in human monocytes and macrophages." (PMID 29203829, 2017). "Since IL-4 plays an important role in the pathogenesis of atopic dermatitis (AD), we further tested whether expression of FoxQ1 is changed in blood monocytes from AD patients compared to healthy donors." (PMID 29203829, 2017).
bladder transitional cell carcinoma (2 papers, 2021 to 2022). The most common morphologic subtype of urinary bladder carcinoma (over 90% of cases). "We showed that FOXQ1 expression could cause activity changes in various cancer-related pathways in 12 different tumor types, such as bladder urothelial carcinoma, prostate adenocarcinoma, skin cutaneous melanoma, and brain lower-grade glioma." (PMID 36118871, 2022). "Compared with the III + IV stage, the FOXQ1 expression level in the I + II stage was higher in bladder urothelial carcinoma and skin cutaneous melanoma and lower in rectum adenocarcinoma, thyroid carcinoma, and testicular germ cell tumors." (PMID 36118871, 2022). "By contrast, its expression was negatively correlated with the stromal and immune score in pancreatic adenocarcinoma, bladder urothelial carcinoma, and stomach adenocarcinoma, which suggested that with an increase in the stromal and immune score, FOXQ1 expression was decreased." (PMID 36118871, 2022). "Foxq1, putative target gene of miR-124, is positively correlated with the expression of MALAT1 in bladder transitional cell carcinoma." (PMID 34422802, 2021). "For example, FOXQ1 expression inhibited activation of the IL6/JAK/STAT3 signaling pathway, IL2/STAT5 signaling pathway, allograft rejection pathway, apical junction pathway, and complement pathway in bladder urothelial carcinoma." (PMID 36118871, 2022).
breast tumor (2 papers, 2016 to 2023). "To examine whether FOXQ1 upregulation is required for FGFR1 signaling-promoted breast tumor growth in vivo, we injected control DCIS-iFGFR1 cells with sh-NC expression and FOXQ1-knockdown DCIS-iFGFR1 cells with sh-FOXQ1-1/2 expression into the mammary gland fat pads of female BALB/c-nu mice." (PMID 36778115, 2023). "Some key genes are densely connected, such as FOXQ1 and SFRP1, which are well-known molecules driving the heterogeneity and progress of breast tumors." (PMID 27786176, 2016).
cutaneous melanoma (2 papers, 2022 to 2025). A primary melanoma arising from atypical melanocytes in the skin. "Kaplan–Meier and Cox analyses suggested that FOXQ1 expression was associated with poor overall survival of cutaneous melanoma and thymoma." (PMID 36118871, 2022). "A Kaplan–Meier cumulative survival curve indicated that FOXQ1 expression was associated with unfavorable prognosis in skin cutaneous melanoma and thymoma." (PMID 36118871, 2022). "Furthermore, Cox regression analysis indicated that FOXQ1 expression was associated with better prognosis in breast invasive carcinoma and kidney renal papillary cell carcinoma but with worse prognosis in cholangiocarcinoma, thymoma, pancreatic adenocarcinoma, and skin cutaneous melanoma." (PMID 36118871, 2022). "Kaplan–Meier and Cox regression analyses indicated that FOXQ1 expression decreased the OS of skin cutaneous melanoma and thymoma patients." (PMID 36118871, 2022).
diabetes (2 papers, 2012 to 2022). "The important role of FOXQ1 in diabetes indicated that the reduced FOXQ1 caused the inhibited osteogenesis of BMSC which was one of the vital mechanisms for diabetic OP." (PMID 36050744, 2022). "To date, the role of FOXQ1 in diabetes or osteogenesis is less investigated." (PMID 36050744, 2022).
gastric adenocarcinoma (2 papers, 2017 to 2022). "Gene expression analysis showed that FOXC2and FOXQ1 transcript levels were significantlyhigher in gastric adenocarcinoma samples thanin normal pair tissues." (PMID 28580309, 2017). "We show that up-regulation of FOXC2 and FOXQ1 are likely to be involvedin the progression of gastric adenocarcinoma." (PMID 28580309, 2017). "However, the clinical significance of FOXQ1 expression level in gastric adenocarcinoma has not been confirmed by an independent study." (PMID 28580309, 2017).
metastatic tumor (2 papers, 2020 to 2022). "Consistent with the suppressive effects of circCRIM1 knockdown, FOXQ1 downregulation significantly reduced lung metastatic tumors in mice (P < 0.05)." (PMID 32061262, 2020). "Our results suggest the FOXQ1-RbBP5 interaction may be a promising therapeutic target for targeting TNBC progression or metastatic tumor recurrence." (PMID 36319643, 2022). "Interestingly, LAMA4 and FOXQ1 have been identified as molecular determinants of metastatic tumor re-initiation in breast cancer." (PMID 36319643, 2022).
nasopharyngitis (2 papers, 2014 to 2021). An inflammatory process that affects the nasopharynx. "The results showed that Foxq1 was significantly upregulated in NPC tissues compared with nasopharyngitis tissues (p < 0.001)." (PMID 33875643, 2021). "Using IHC staining, Foxq1 expression was quantified in control and NPC tissues, containing 114 NPC patient samples (7, 24, 38, and 45 cases of grade I, II, III, and IV) and 40 nasopharyngitis samples." (PMID 33875643, 2021). "Foxq1 was found to be predominantly overexpressed in the cytoplasm and membranes of NPC cells and was less expressed in non-cancer nasopharyngitis biopsy samples." (PMID 25098939, 2014). "Immunohistochemistry (IHC) was also performed to detect Foxq1 expression in 178 clinical NPC specimens and 55 non-cancer nasopharyngitis biopsy samples." (PMID 25098939, 2014).
pancreatic adenocarcinoma (2 papers, 2019 to 2022). "In addition, FOXQ1 expression was associated with poor disease-free survival of pancreatic adenocarcinoma." (PMID 36118871, 2022). "FOXQ1 expression was also associated with poor DFS in pancreatic adenocarcinoma." (PMID 36118871, 2022). "The findings suggested that FOXQ1 expression was related to poor DFS in pancreatic adenocarcinoma." (PMID 36118871, 2022). "Cox regression analysis demonstrated that FOXQ1 expression was related to good DFS in uterine corpus endometrial carcinoma and poor DFS in colon adenocarcinoma and pancreatic adenocarcinoma." (PMID 36118871, 2022). "Normalized mRNA expression data from TCGA studies of breast, prostate, lung, colorectal and pancreatic adenocarcinomas was downloaded for ZEB1, ZEB2, SNAI1, SNAI2, TWIST1, FOXQ1 and FOXC218,19." (PMID 31780722, 2019).
pancreatic ductal adenocarcinoma (2 papers, 2013 to 2019). An infiltrating adenocarcinoma that arises from the epithelial cells of the pancreas. "Also, FOXQ1 was significantly inversely correlated with stromal score in pancreatic ductal adenocarcinoma." (PMID 31780722, 2019).
thyroid cancer (2 papers, 2022).
asthma (1 paper, 2021). "Two transcription factors, forkhead box Q1 (Foxq1) and nuclear factor of activated T cells 2 (Nfatc2), served important regulatory roles in asthma." (PMID 34285702, 2021). "However, no studies have reported the roles of Foxq1 in asthma; further studies with biological experiments are needed to illustrate its exact molecular mechanism." (PMID 34285702, 2021).
cerebrovascular disease (1 paper, 2025). "The translational relevance of our findings would be strengthened by validation in human brain EC models and examination of FOXQ1 expression patterns in human cerebrovascular disease." (PMID 40884816, 2025).
colon adenocarcinoma (1 paper, 2022). "The validation results of Oncomine suggested that FOXQ1 was upregulated in colon adenocarcinoma and liver hepatocellular carcinoma and downregulated in kidney cancer and prostate adenocarcinoma, which was consistent with TCGA results." (PMID 36118871, 2022). "FOXQ1 has been reported to be highly significantly expressed in colon adenocarcinoma and rectum adenocarcinoma." (PMID 36118871, 2022).
colon adenoma (1 paper, 2013). An adenoma that arises from the colon. "The mRNA level of FOXQ1 has been shown to be induced in colon adenoma and carcinoma samples." (PMID 23555880, 2013).
ductal carcinoma (1 paper, 2017). "Expression of FOXQ1 was detected in in ductal carcinoma, not in normal ductal cells, acinar cells and islets cells." (PMID 29050264, 2017).